TYR (tyrosinase)
Diseases named in the same sentence as TYR in open-access papers (continued):
Sharing a sentence is not in itself a finding about the gene and the disease.
meningioma (2 papers, 2023 to 2025). A generally slow growing tumor attached to the dura mater. "Similarly, when comparing the amino acid profiles of patients with meningioma to the control group, the differences observed concerned endogenous amino acids (GLN, CIT, GABA, ORN, ASP) and exogenous amino acids (THR, MET, LYS, AAA, PHE, C-C, TYR)." (PMID 38067430, 2023).
ocular albinism type 1 (2 papers, 2005 to 2019). "Six genes are associated with autosomal recessive OCA (TYR, OCA2, TYRP1, SLC45A2, SLC24A5 and LRMDA), and one gene, GPR143, is associated with X-linked ocular albinism (OA)." (PMID 30679655, 2019).
oral carcinoma (2 papers, 2024). "This study delves into the potential therapeutic applications of S. betaceum by analyzing its polyphenolic content (TPC), total flavonoid content (TFC), anti-skin aging activities against key enzymes like elastase, tyrosinase, and hyaluronidase, and its cytotoxic effects on oral carcinoma cells." (PMID 39204651, 2024).
partial albinism (2 papers, 2019 to 2022). "At the same time, 13 individuals who were compound heterozygous for TYR p.(Met252Arg) and p.(Ser192Tyr)/p.(Arg402Gln) alleles all displayed clinical features of partial albinism, suggesting an additive impact of the p.(Ser192Tyr) and p.(Arg402Gln) variants on tyrosinase function." (PMID 35027574, 2022).
PEComas (2 papers, 2007 to 2024). "PEComas are immunoreactive for both smooth muscle (desmin, SMA, muscle-specific-actin, muscle myosin, and calponin) and melanocytic (HMB-45, Melan-A/MART-1, tyrosinase, and MITF) markers." (PMID 39759135, 2024).
prostate tumors (2 papers, 2008 to 2025). "Further studies on the use of quercetin nanocapsules in other high tyrosinase-expressing cancers, such as prostate tumours, are also warranted." (PMID 40732270, 2025).
renal cell carcinoma (2 papers, 2013 to 2021). "Sorafenib is a tyrosinase inhibitor that has been proven effective against renal cell carcinoma (RCC)." (PMID 34842684, 2021).
skin hypopigmentation (2 papers, 2019 to 2022). "Tyrosinase catalyzes the rate-limiting step in melanogenesis, and the inhibition of tyrosinase is the most efficient strategy for the inhibition of melanogenesis and the development of skin hypopigmentation agents." (PMID 35892714, 2022). "Interestingly, one patient had skin hypopigmentation (patient 27, LPS 1600, V0) though no T cell response to 12MP or tetanus peptide ex vivo, but positive to tyrosinase (DAEK) with in vitro stimulated ELIspot assay in PBMC and SIN." (PMID 31248461, 2019).
soft tissue sarcoma (2 papers, 2021 to 2024). A malignant neoplasm arising from muscle tissue, adipose tissue, blood vessels, fibrous tissue, or other supportive tissues excluding the bones. "In that circumstance, RNA expression of TYR, CALD1 and CD34 has been shown to be discriminatory between spindloid oral melanoma and soft tissue sarcoma lesions [LOE 5, OEG D]." (PMID 38645640, 2024). "In conclusion, this study determined that relative RNA expression levels of TYR, CD34, and CALD1 discriminate between canine oral melanomas and soft tissue sarcomas." (PMID 34422947, 2021).
tuberculosis (2 papers, 2021). A chronic, recurrent infection caused by the bacterium Mycobacterium tuberculosis. "Ethionamide, a secondary anti-tuberculosis agent used to treat multidrug-resistant tuberculosis, shares a chemical similarity with tyrosinase inhibitors, and reduces melanin content." (PMID 33918792, 2021).
Waardenburg syndrome (2 papers, 2011 to 2020). A disorder characterized by varying degrees of deafness and minor defects in structures arising from neural crest, including pigmentation anomalies of eyes, hair, and skin. "Thus, possible candidates for white coat colour (KIT on BTA6, KITLG on BTA5, PMEL on BTA5, TYR on BTA29) and other Waardenburg syndromes (WS) including PAX3 (WS1, WS3; on BTA2), EDNRB (WS4a; on BTA12), EDN3 (WS4b; on BTA13) and SOX10 (WS2e, WS4c; on BTA5) could be clearly excluded." (PMID 22174915, 2011).
Waardenburg syndrome type 2 (2 papers, 2015 to 2020). Waardenburg syndrome type 2 (WS2) is an autosomal dominant subtype of Waardenburg syndrome (WS), characterized by varying degrees of deafness and pigmentation anomalies of eyes, hair and skin, but without dystopia canthorum. "In contrast, the phosphorylation of MITF on serine 298, a mutation related to Waardenburg syndrome type 2 (WS2), by glycogen synthase kinase 3 enhances the binding to the tyrosinase promoter." (PMID 26024475, 2015).
acanthosis nigricans (1 paper, 2022). A melanotic cutaneous lesion that develops in the axilla and other body folds. "Hyperpigmentation is caused by tyrosinase; thus, inhibition of tyrosinase activity can be a good therapeutic approach for treating cutaneous hyper pigmentary disorders such as diabetic dermopathy and acanthosis nigricans." (PMID 35335362, 2022).
acral melanomas (1 paper, 2022). "Over expression of NQO1 in acral melanomas and human melanocytes is reported to increase tyrosinase activity, but the extent to which this and other antioxidant enzymes contribute to the effects of SFN on pigment cells has not been determined." (PMID 36291795, 2022).
adenoma (1 paper, 2013). A neoplasm arising from the epithelium. "Nevertheless, these results identify a tyrosinase expressing lung cell population in neonate mice where mutation of BRAF led to adenoma development." (PMID 23825589, 2013). "In this study, we show that conditional expression of BRAFV600E under the control of a tyrosinase-promoter driven transgenic system, induced bronchiole epithelial hyperplasia and adenoma development." (PMID 23825589, 2013). "In summary, we show evidence for the existence of tyrosinase and SP-C-expressing cells in the lungs of neonate mouse where activation of oncogenic BRAFV600E induces adenoma development." (PMID 23825589, 2013).
adrenocortical tumor (1 paper, 2010). "This can be distinguished from an adrenocortical tumor by positivity for other melanocytic makers such as S-100, HMB-45, tyrosinase and negativity of calretinin, synaptophysin and inhibin." (PMID 20687934, 2010).
angiomyolipoma (1 paper, 2013). A neoplasm with perivascular epithelioid cell differentiation often associated with tuberous sclerosis. "Angiomyolipoma reacts with HMB45, Melan-A, tyrosinase and S100 protein." (PMID 24179528, 2013).
Arthritis (1 paper, 2021). Inflammation of a joint. "Among 35 MD-associated genes with drug-interaction data, four MD-specific genes interacted with drugs associated with arthritis: NR3C1 (N = 6), NRG1 (N = 2), CD40 (N = 2), TYR (N = 1)." (PMID 34603368, 2021).
complication (1 paper, 2022). Any disease or disorder that occurs during the course of, or because of, another disease, treatment, or procedure. "Thus, discovery of tyrosinase inhibitors is important for tyrosinase control and treatment of melanin-related skin complications." (PMID 35937399, 2022).
deafness (1 paper, 2015). An inherited or acquired condition characterized by the complete loss of the ability to hear from one or both ears. "Across species, the genes identified with deafness or white pigmentation patterns include MITF, PMEL, KIT, EDNRB, CDH23, TYR, and TRPM1 in dog, cat, horse, cow, pig, sheep, ferret, mink, camelid, and rabbit." (PMID 26664958, 2015).
Hunter syndrome (1 paper, 2012). "In couple number 3, the female was a carrier of a deletion of exons 4–7 in the IDS gene, and both members of the couple were also carriers of different mutations in the TYR gene, requiring simultaneous PGD for both Hunter syndrome and oculocutaneus albinism (a recessive disorder)." (PMID 23320174, 2012).
Hyperkeratosis (1 paper, 2020). Hyperkeratosis is a histopathological term defining a thickened stratum corneum and may be present in many different skin conditions, with many possible overlaps. "It decreases the size and number of comedones by altering follicular hyperkeratosis as well as reducing post-inflammatory hyperpigmentation due to its anti-tyrosinase activity." (PMID 32724156, 2020).
hyperuricemia (1 paper, 2025). An abnormally high level of uric acid. "The enhanced tyrosinase inhibition rate (up to 50.02 ± 0.76% at 100 μg/mL) and xanthine oxidase inhibition rate (34.04 ± 1.43%) in fermented A. argyi leaves make solid-state fermented leaves potential candidates against cosmetic/dermatological and hyperuricemia-related applications, respectively." (PMID 41464969, 2025).
hypothyroidism (1 paper, 2023). Abnormally low levels of thyroid hormone. "Furthermore, Cu deficiency can lead to hypothyroidism by inducing oxidative stress and decreasing thyroxine synthesis by limiting tyrosinase availability." (PMID 37711903, 2023).
injury (1 paper, 2024). Damage inflicted on the body as the direct or indirect result of an external force, with or without disruption of structural continuity. "In parallel, we did not identify a direct biologicalconnectionbetween Ncan–APOH and TYR or Ncan–TMEM 212 and FSIP2in the context of brain injury." (PMID 38870483, 2024).
Intervertebral disk degeneration (1 paper, 2023). The presence of degenerative changes of intervertebral disk. "Overall, the intrinsic anti-tyrosinase and anti-elastase activities and the ability to protect from oxidative stress-induced damages justify future investigations of these “active per sé” formulations in treating or preventing intervertebral disk degeneration." (PMID 36969863, 2023).
keloid (1 paper, 2023). An irregularly shaped, elevated mark on the skin caused by deposits of excessive amounts of collagen during wound healing. "This study demonstrates the feasibility of tyrosinase inhibitors as one of the therapeutic options for the treatment of keloids." (PMID 38046417, 2023). "Tyrosinase inhibitors can inhibit the formation of keloids by targeting the Akt/PI3K/mTOR pathway, the MAPK/ ERK pathway." (PMID 38046417, 2023).
keratinocyte carcinoma (1 paper, 2024). A skin cancer arising from the keratin-producing cells of the epidermis. "Most of these genes are pigmentation-related genes (i.e., SLC45A2, TYR, OCA2, MC1R, and ASIP) and have a biological importance of lighter pigmentation in susceptibility to keratinocyte carcinoma." (PMID 38182794, 2024).
lateral sclerosis (1 paper, 2012). Primary lateral sclerosis (PLS) is an idiopathic non-familial motor neuron disease characterized by slowly progressive upper motor neuron dysfunction leading to spasticity, mild weakness in voluntary muscle movement, hyperreflexia, and loss of motor speech production. "Expression of SLC24A5, MMP115, and TYR, and genes for crystalline alphaB (CRYAB), Shikimate 5-dehydrogenase and amyotrophic lateral sclerosis 2 (ALS2) were commonly depressed in AV and CV samples relative to BL controls." (PMID 22500953, 2012).
liver cancer (1 paper, 2025). An epithelial or non-epithelial malignant neoplasm that arises from the liver. "Research on the application of tyrosinase inhibitors in liver cancer has been conducted in 80 countries and regions." (PMID 40388796, 2025). "Using CiteSpace, we came up with the 50 most reliable citation bursts for tyrosinase inhibitors in liver cancer applications." (PMID 40388796, 2025). "Importantly, 19 of these papers are currently at peak citation, implying that tyrosinase inhibitors in liver cancer will continue to be of interest in the future." (PMID 40388796, 2025).
lung adenoma (1 paper, 2013). A benign, well circumscribed epithelial neoplasm that arises from the bronchus or the lung parenchyma. "Here we show that in the course of modeling malignant melanoma in a inducible tyrosinase promoter transgenic system, activation of BRAFV600E oncogene in 2.5 days old mice by 4-OH-tamoxifen administration, make them susceptible to develop lung adenomas." (PMID 23825589, 2013). "During characterization of the mice’s phenotype, the occurrence of lung adenomas in tyrosinase promoter-driven transgenic mice (Tyr::CreERT2) expressing BRAFV600E, prompted a detailed analysis of transgene expression in the lung." (PMID 23825589, 2013).
Lupus (1 paper, 2023). "Although lesser ODs were detected for ANA, TG2, TG6, heparin, α-myosin, chondroitin sulfate, Lupus RO-60, fibrinogen, tyrosinase, β catenin, thyroid peroxidase, claudin 7, sulfatides, somatotropin, S100B, somatostatin and actin, their p values were still very, very significant." (PMID 37845267, 2023).
lymphoma (1 paper, 2018). A malignant (clonal) proliferation of B- lymphocytes or T- lymphocytes which involves the lymph nodes, bone marrow and/or extranodal sites. "These mice carry an inactivating mutation in the tyrosinase coding gene which prevents hair pigmentation and drastically reduces quenching of bioluminescent signals from the lymphoma." (PMID 29721165, 2018).
MEDNIK syndrome (1 paper, 2025). "Copper deficiency can lead to decreased tyrosinase activity as well as reduced phenindione and melanin production; therefore, patients with MEDNIK syndrome have reduced skin pigmentation, and in severe cases, hair bleaching can occur." (PMID 40901618, 2025).
medulloblastoma (1 paper, 2026). A malignant, invasive embryonal neoplasm arising from the cerebellum. "Specifically, DIPG, ATRT (TYR, MYC), and medulloblastoma (SHH) had increased levels of CD4 expression, also known to be expressed by human monocytes and macrophages, while CD8 expression tended to be decreased, except in the case of WNT-activated medulloblastoma." (PMID 41541220, 2026).
mesenchymal tumors (1 paper, 2004). "Zamecnik and Michal found immunoreactivity for HMB-45 in four distinctively hyalinized epithelioid mesenchymal tumors of the uterus, but all four cases were negative for the other three melanogenesis markers tested (Melan-A, tyrosinase and micropthalmia transcription factor)." (PMID 15494070, 2004).
myasthenia gravis (1 paper, 2020). Myasthenia gravis (MG) is a rare, clinically heterogeneous, autoimmune disorder of the neuromuscular junction characterized by fatigable weakness of voluntary muscles. "Our results demonstrated for the first time that Aglianico leaves are important sources of phenols that could be used to prevent oxidative stress and be potentially helpful in diseases treatable with tyrosinase and cholinesterase inhibitors, like myasthenia gravis or Alzheimer’s." (PMID 32759838, 2020).
peripheral nerve tumors (1 paper, 2023). "In contrast, peripheral nerve tumors showed negative or weak staining for tyrosinase." (PMID 37504268, 2023).
pineoblastoma (1 paper, 2023). Pineoblastoma is a rare, malignant type of supratentorial primitive neuroectodermal tumor (sPNET), found mainly in children (less than 10% of cases are reported in adults), and located in the pineal region of the brain but that can metastasize along the neuroaxis. "Pineoblastomas are described as having four molecular subgroups in the latest WHO classification and ATRTs have been divided into the tyrosinase (TYR), MYC, and SHH subgroups." (PMID 37835574, 2023).
pterygium (1 paper, 2022). A wedge-shaped fibrovascular lesion arising from the bulbar conjunctiva and extending to the cornea. "In active pterygium, genes involved with immune and inflammatory response (CXCL9 and PLA2G2D), angiogenesis (SERPINB5 and BM4), keratinization (DSG1), response to UV light (TYR) and negative regulation of apoptotic process (PIM1) are up regulated in relation to atrophic pterygium." (PMID 34997134, 2022).
Rb (1 paper, 2019). "This is the first study suggesting that these genes, FGFR4, NQO1, ACADS CX3CR1, GBE1, KRT85, and TYR genes, may play a role in the etiology of Rb." (PMID 31207142, 2019).
retinoschisis (1 paper, 2018). An inherited or acquired disorder characterized by splitting of the retina into two layers. "Further, a recent report has shown the existence of a genetic modifier (Tyrosinase) that play an important role in determining the severity of schisis in a retinoschisis mouse model." (PMID 29851975, 2018).
skin atrophy (1 paper, 2025). The degeneration and thinning of the epidermis and dermis. "Despite its known efficacy through the combined actions of hydroquinone (a tyrosinase inhibitor), tretinoin (a keratinocyte turnover promoter), and corticosteroids (anti-inflammatory agents), concerns over irritation, rebound hyperpigmentation, and skin atrophy limit its long-term application." (PMID 40826371, 2025).
squamous cell carcinoma of the skin (1 paper, 2012). "The association of the rs1042602 cSNP of TYR with squamous cell carcinoma of the skin in Caucasians and with pigmentation variation in the south Asian population has been documented." (PMID 22734612, 2012).
ulcer (1 paper, 2026). "Molecular docking studies against ulcer-associated targets predicted camphor's superior binding affinity for MMP9 (-7.8 kcal/mol) compared to ranitidine (-6.3 kcal/mol), with stable hydrogen bonding interactions involving TYR A:111 and TYR A:458." (PMID 42064812, 2026).
ulcerative colitis (1 paper, 2025). An inflammatory bowel disease involving the mucosal surface of the large intestine and rectum. "Interestingly, although TYR itself appears to have a tumour-suppressive effect, TYR kinase, which phosphorylates it, has been previously implicated in the development of adenomatous polyps, ulcerative colitis and CRC." (PMID 41561540, 2025).
uveitis (1 paper, 2023). An inflammatory process affecting a part of or the entire uvea. "Moreover, increased serum positivity for ARA has been described in TBU, and intraocular fluid from IGRA-positive uveitis patients more frequently contained anti-tyrosinase autoantibody that was significantly associated with CME occurrence." (PMID 38983011, 2023).
vulvar melanoma (1 paper, 2022). A usually pigmented, nodular or polypoid malignant neoplasm that originates from melanocytes and arises from the vulva. "Therefore, diagnosis of amelanotic vulvar melanoma requires IHC testing of HMB-45, protein S-100, vimentin, MART-1, and tyrosinase." (PMID 36358637, 2022).
xerosis (1 paper, 2022). "In addition to tyrosinase, the extracts were screened for their elastase inhibitory activities since xerosis is a condition caused by a loss of elasticity in the skin of diabetics." (PMID 35335362, 2022).
Zinc deficiency (1 paper, 2025). A deficiency of the essential metal Zinc; an essential cofactor for many enzymes. "While zinc deficiency is associated with brittle hair and loss of hair, copper deficiency is associated with depigmentation (silver-grey or lighter), as the tyrosinase involved in melanin production is copper-dependent." (PMID 41401733, 2025).